HDAC2 (histone deacetylase 2)
Diseases named in the same sentence as HDAC2 in open-access papers (continued):
Sharing a sentence is not in itself a finding about the gene and the disease.
breast cancer (continued). "Our observations stay in line with previously reported enhanced antitumor immunity in triple-negative breast cancers achieved by HDAC2 knockout in the breast cancer mice models." (PMID 39063083, 2024). "HDAC2 was significantly upregulated in breast cancer tissues compared to non-cancerous tissues and a normal cell line, whereas miR-646 expression is decreased in breast cancer cells." (PMID 36968022, 2023). "We therefore sought to investigate whether the inhibition of HDAC2, HDAC4, or KDM1A would restore the expression of PHLDA1 in lapatinib-resistant HER2+ breast cancer cells." (PMID 37047202, 2023). "Furthermore, MDA-MB-231 and MCF-7 treated with combined concentrations of genistein and SFN resulted in the decreased expression of HDAC2, HDAC3, KLF4, and hTERT, suggesting the alterations of epigenetic mechanisms in breast cancer cells." (PMID 36765652, 2023). "In breast cancer, high levels of HDAC2 were closely correlated with lymph node metastasis and high levels of multidrug resistance protein." (PMID 36968022, 2023). "Although the specific mechanism and pathway interactions through which PIMREG promotes breast cancer remain unknown, our study identified correlations between PIMREG and MTA2, and HDAC2." (PMID 37483962, 2023). "PEITC-treated breast cancer cells displayed the reactivation of CDH1 that could be due to the decreased activity of DNMT1, DNMT3a, DNMT3b, HDAC1, and HDAC2." (PMID 36765652, 2023). "In our study, we found decreased HDAC2 and HDAC8 expression, inhibited HDACs activity, decreased DNMT3b expression, and decreased DNMTs activity, indicating that inulin dietary treatment induced protective epigenetic changes in mammary tumor cells in mice." (PMID 37240357, 2023). "The high expressions of HDAC2 and HDAC6 in mammary carcinomas in female dogs may be useful information for research involving therapeutic targets with iHDACs since their inhibition favors hyperacetylation and transcription of tumor suppressor genes." (PMID 38028583, 2023). "ARAP1-AS1 is overexpressed in breast cancer cells and ARAP1-AS1 silencing results in inhibited proliferation, blocked migration, and strengthened apoptosis of breast cancer cells via the microRNA-2110/histone deacetylase 2/perilipin 1 axis." (PMID 35291911, 2022). "In addition, correlation analysis from bc-GenExMiner v4.5 revealed that the expression of HDAC2, as well as JAK1, JAK2, and STAT1, was significantly correlated with that of PD-L1 in breast cancer." (PMID 34365463, 2021). "Moreover, HDAC2 transcription is promoted by the YAP/RUNX1 complex to induce chemoresistance and stemness in breast cancer, indicating that HDAC2 plays a role in cell stem progress." (PMID 34993131, 2021). "Increased expression of HDAC1, HDAC2, HDAC3 and HDAC6 are reported in several cancers including colon, prostate and breast cancer and inhibition of HDACs potentially could target proliferation, differentiation, angiogenesis, and migration." (PMID 33802026, 2021). "To further explore whether HDAC2 affected the biological functions of breast cancer cells, we used CRISPR/Cas9 gene editing method to construct a mouse TNBC cell strains (4T-1) that stably knocked out HDAC2 (HDAC2-KO)." (PMID 34365463, 2021). "To identify whether histone deacetylases have direct relationships with the prognosis of breast cancer patients, we assessed the HDAC1, HDAC2, and HDAC3 protein expression data from a combined cohort of 161 breast cancer cases." (PMID 32686908, 2020). "In addition, overexpressed HDAC2 and SIRT2 as well as nearly depleted SIRT3 were observed in the aggressive basal-like breast cancer cells." (PMID 33194676, 2020). "Since HDAC1, HDAC2, and HDAC3 are the most common histone deacetylases in human tissues with a relatively high abundance and have already been reported elsewhere to be potential oncogenes in breast cancer, our studies mainly focus on these three HDAC proteins." (PMID 32686908, 2020).
breast cancer (continued). "Thus, HDAC1, HDAC2, and HDAC3 all displayed typical oncogenic characteristics and were important in the early development of breast cancer and later survival of patients." (PMID 32686908, 2020). "We next examined the role of HDAC2 and HDAC5 in the survival of ER+ breast cancer cells." (PMID 29326587, 2017). "We postulated that when REST and HDAC2 are lacking in breast cancer, enhance expression of Nav1.5 and nNav1.5 promotes aggressiveness." (PMID 28785170, 2017). "Collectively, these results suggest that aberrant expression of HDAC2 and HDAC5 may affect the effectiveness of hormone therapy in patients with ER+ breast cancer." (PMID 29326587, 2017). "Dysregulation of HDAC2 and HDAC5 can be found in ER+, estrogen-independent, tamoxifen-resistant breast cancer cells and high expression of HDAC2 correlates with poor clinical outcomes in ER+ tamoxifen-treated breast cancer patients." (PMID 29326587, 2017). "In this study, we found that ER+, hormone-independent, tamoxifen-resistant MCF7-TamC3 cells exhibit increased expression of HDAC2, HDAC5, and survivin, but show decreased expression of miR-125a-5p, as compared to the parental tamoxifen-sensitive MCF7 breast cancer cells." (PMID 29326587, 2017). "Possibly, combined inhibition of multiple histone-modifying enzymes, such as LSD1, HDAC2 and SIRT1, could lead to improved treatment of breast cancer patients." (PMID 25139823, 2014). "In sum, the loss of HDAC1 and HDAC2 increases C3 and NCOA2, but not CLU, ERBB2, MYC, or PGR, providing evidence that C3 and NCOA2 are repressed in breast cancer cells by the HDAC1/2 components of the Sin3A repressive complex." (PMID 20920219, 2010). "In addition, HDAC2 and HDAC3 were shown to facilitate the inhibition of vascular endothelial growth factor (VEGF) signaling, which promotes angiogenesis to support tumor progression, in breast cancer cells in vitro." (PMID 40165290, 2025). "Moreover, breast cancer tissues show significantly higher HDAC2 expression than normal breast tissue." (PMID 37764768, 2023). "For example, in breast cancer cells, HDAC1–3 are inhibited by SFN to induce cell apoptosis; in skin cells, HDAC1–4 are regulated by SFN; in the cochlea, SFN inhibits HDAC2, 4, and 5; and in colon cancer models, SFN downregulated only HDAC3 to prevent DNA damage repair." (PMID 36006435, 2022). "To clarify the mechanism of epigenetic modification in regulating PDK1 in breast cancer, we address following questions: Firstly, to explore whether PDK1 expression is dysregulated in breast cancer and the aberrant expression of PDK1 is regulated by histone deacetylase 2 (HDAC2) and EZH2." (PMID 35892859, 2022). "Additionally, in breast cancer, the transcription factor TWIST recruits an RBBP7/4-MTA2/Mi-2/HDAC1/HDAC2 complex to the proximal regions of the E-cadherin promoter for transcriptional repression via an interaction with RBBP7, which promotes breast cancer cell invasion and metastasis." (PMID 34736517, 2021). "Finally, COPS5, HDAC2, and NONO were selected as hub TFs because of their significantly higher expression in breast cancer, lower survival probability in the high-risk group, and specific target genes." (PMID 34993131, 2021). "Furthermore, the expression of HDACs (HDAC1 and HDAC2) that interact with the PRC2 complex was also negatively correlated with PTEN expression, consistent with the result of TSA treatment in breast cancer cell lines." (PMID 33750924, 2021). "Our results showed that the expression of HDAC1/HDAC2/HDAC3 increased significantly in the tumor tissues compared to the adjacent non‐neoplastic breast tissue, indicating that the three histone deacetylases play vital roles in the initiation and development of breast cancer." (PMID 32686908, 2020).
breast cancer (continued). "BRCA1 R1699Q, a point mutation found in non-familial breast cancer patients, results in the failure of BRCA1 to recruit HDAC2 to the miR-155 promoter leading to histone acetylation and a subsequent increase in miR-155 expression contributing to breast tumourigenesis." (PMID 30323900, 2018). "Activated AR has been shown to cooperate with HDAC1, HDAC2, or HDAC3 to downregulate E-cadherin and promote the migration of non-metastatic breast cancer cells." (PMID 39000339, 2024). "We further analyzed the independent breast cancer gene expression dataset (GSE27447) from the public GEO database and were surprised to find that the strongest negative correlation was between HDAC2 and miR-148a (r = −0.52, p < 0.05)." (PMID 35892859, 2022). "Consistent with the bioinformatics analysis, COPS5, HDAC2, and NONO were more highly expressed in breast cancer cell lines than in normal breast epithelial cells." (PMID 34993131, 2021). "Results of the TF–target gene network, expression panel, and survival analysis revealed that COPS5, HDAC2, and NONO served as the hub TFs for breast cancer." (PMID 34993131, 2021). "In contrast, the role of HDAC2 and HDAC5 in the development of hormone therapy resistance in ER+ breast cancer has not yet been studied in details." (PMID 29326587, 2017). "Chrysin was proven to be an HDAC2/8 dual inhibitor (HDAC2 EC50 = 129.0 μM; HDAC8 EC50 = 40.2 μM), without showing any activity on HDAC1, and was able to suppress cell growth while promoting differentiation in human breast cancer MDA-MB-231 cells." (PMID 36077415, 2022). "Moreover, three hub TFs (COPS5, HDAC2, and NONO) were isolated as the prognostic biomarkers of breast cancer through the TF–target gene network, expression profile, and survival probability of the 10 prognosis-related TFs in breast cancer." (PMID 34993131, 2021). "Upon further analysis, three hub TFs, COPS5, HDAC2, and NONO were identified and were demonstrated to be highly expressed in human breast cancer samples when compared to adjacent tissues using western blotting and quantitative reverse transcription polymerase chain reaction (qRT-PCR)." (PMID 34993131, 2021). "COPS5, HDAC2, and NONO were recognized as hub TFs in breast cancer." (PMID 34993131, 2021). "To further confirm whether COPS5, HDAC2, and NONO performed similar functions in normal and breast cancer cells, we measured the mRNA and protein levels in breast cancer and normal breast epithelial cells." (PMID 34993131, 2021). "Experimental study in vivo had demonstrated that decreased HR efficiency could lead to breast cancer progression However, whether RAD51 was acetylated by HDAC2 or SIRT2 was not discussed in detail." (PMID 33194676, 2020). "Therefore, quantitative real-time PCR was performed to determine whether HDAC2, HDAC3, and HDAC6 (but not HDAC1) can regulate survivin gene expression in breast cancer cells." (PMID 27065869, 2016).
asthma (50 papers, 2010 to 2025). "Reduced HDAC2 activity is associated with the elevation of inflammatory gene expression in patients with severe asthma." (PMID 37312162, 2023). "The modulation of inflammatory features was associated with significant inhibition of neutrophilia and oxidative and nitrative stress, decrease in HDAC2, and increase in IL-17 levels that are usually associated with steroid-resistant asthma." (PMID 36060927, 2022). "CIH can induce oxidative stress in asthma, stimulate the p38 pathway, cause GR dysfunction, and reduce the expression levels of histone deacetylase (HDAC2)." (PMID 34512379, 2021). "Molecular mechanisms underlying the reduction in HDAC2 expression in severe asthma have been elucidated." (PMID 32112175, 2020). "Passive smoking causes poor responses to steroids in asthma patients by increasing the leukotriene level and oxidative stress-related mechanisms, such as histone deacetylase-2 function via activation of the phosphoinositide-3-kinase/Akt pathway." (PMID 29872096, 2018). "Notably, reduced HDAC2 levels have been linked to corticosteroid resistance in asthma patients, positioning HDAC2 as a promising therapeutic target." (PMID 40806756, 2025). "Moreover, defective HDAC2 activity is found in corticosteroid-insensitive severe asthma phenotypes and mice with HDAC1- deficient T-cells present increased eosinophil recruitment and Th2 cytokine production." (PMID 33673725, 2021). "In addition to differential HDAC expression, single nucleotide polymorphisms in both HDAC1 and HDAC2 have been observed in patients with asthma." (PMID 34968229, 2019). "Various human asthma and murine models have been reported to decrease HDAC2 expression and specific enzyme activity." (PMID 38178983, 2023). "In inflammatory lung diseases, such as COPD and severe asthma, a reduction in the HDAC2 protein level or HDAC2 activity is commonly observed." (PMID 37312162, 2023). "In steroid-resistant asthma, glucocorticoid receptor β contributes to steroid resistance by inhibiting HDAC2 expression." (PMID 37312162, 2023). "Interconnected with influx of inflammatory mediators and increase in immune cells as it occurs in steroid insensitive asthma are the depletion of the enzyme HDAC2 and elevation of the proinflammatory cytokine IL-17." (PMID 36060927, 2022). "Theophylline improves steroid sensitivity in both COPD and asthma and thereby decreases oxidative stress by increasing the expression and activity of HDAC2." (PMID 35681424, 2022). "For instance, the expression of HDAC2 was dramatically reduced in patients with severe asthma and COPD." (PMID 36012240, 2022). "One strategy used to bypass steroid resistance in airway diseases involves activating HDAC2 and reversing the post-translational oxidative modifications of HDAC2, which represents a possible therapeutic principle for the treatment of asthma and COPD." (PMID 36421423, 2022). "Third, reduced HDAC2 activity leads to lower steroid sensitivity in either asthma or COPD, and can be reversed by theophylline, roxithromycin, or miR-223 knock-down." (PMID 35681424, 2022). "The expression of HDAC2 was significantly reduced in the asthma model group (p < 0.0001), was downregulated in Dex-treated mice (p < 0.01) and was restored by Dex and further potentiated by R406 treatment (p < 0.0001)." (PMID 35600871, 2022). "Several strategies have been identified to restore HDAC2 activity and corticosteroid sensitivity in asthma and COPD." (PMID 34572965, 2021). "According to several studies, HDAC2 activity is decreased in alveolar macrophages, peripheral blood mononuclear cells, and bronchial biopsies of asthma patients." (PMID 34016172, 2021). "Several studies have shown that the striking interaction between HDAC2 and IL-17 A forms a vicious cycle, leading to the exacerbation of asthma." (PMID 34016172, 2021).
asthma (continued). "There is evidence for the increased oxidative stress and peroxynitrite formation in COPD and severe asthma, and reduced HDAC2 activity due to HDAC2 tyrosine nitration, and enhanced IL-8 gene expression in bronchial epithelial cells." (PMID 33802941, 2021). "The current follow-up study investigated the mechanism by which CpG-ODNs regulate HDAC2 expression/activity and modulates subsequent inflammatory responses in a mouse model of CS-related asthma and human bronchial epithelial (HBE) cells." (PMID 34016172, 2021). "Overall, CpG-ODNs and BUD synergistically improved adverse CS-exposure asthma outcomes and inhibited, at least in part, RORt-mediated Th17 response by restoring HDAC2 expression and activity, consequently ameliorating GCs insensitivity." (PMID 34016172, 2021). "It is known that IL-17 A modulates the protective effects of HDAC2 on airway inflammation in asthma and that HDAC2 activation and/or IL-17 A downregulation can prevent allergic airway inflammation." (PMID 34016172, 2021). "HDAC inhibitors, particularly HDAC2, are potential targeted therapies against asthma but the results of the clinical trials so far are controversial." (PMID 33673725, 2021). "This study demonstrates that PI3K inhibitors ameliorate GC insensitivity in severe asthma by restoring HDAC2 activity and inhibiting the phosphorylation of nuclear signaling transcription factors." (PMID 32112175, 2020). "COPD and asthma patients with lower HDAC2 activity compared to healthy controls are less sensitive to corticosteroids than patients with higher HDAC2 activity levels." (PMID 32509795, 2020). "HDAC2 protein activity was significantly lower in the asthma group than in the normal group (p < 0.05) and markedly lower in the severe asthma group than in the mild/moderate asthma group (p < 0.01)." (PMID 32112175, 2020). "HDAC2 expression was down-regulated in pulmonary inflammatory diseases such as chronic obstructive pulmonary disease and asthma." (PMID 32051729, 2020). "In asthmatic patients who smoke, tyrosine nitration of HDAC2 is inhibited, which appears to be an important mechanism of GC insensitivity in this subtype of asthma." (PMID 32112175, 2020). "Histone deacetylase 2 (HDAC2) mRNA is decreased in bronchoalveolar lavage cells from steroid-resistant patients with asthma." (PMID 31597362, 2019). "In summary, the expression of HDAC1 and HDAC2 in asthma is either slightly increased or decreased, and HAT activity is slightly increased." (PMID 34968229, 2019). "In severe asthma and asthmatics who smoke, HDAC2 is reduced, thus preventing corticosteroids from suppressing inflammation." (PMID 26075017, 2015). "Collectively, our results indicated that(OH)2D3might be useful as a novel HDAC2 activator in thetreatment of asthma." (PMID 25923460, 2015). "There is also a defect in HDAC2 function in patients with severe asthma and in asthmatic patients who smoke." (PMID 27713276, 2010). "Theophylline also appears to reduce the formation of peroxynitrite and this provides a further mechanism for increasing HDAC2 function in asthma." (PMID 27713276, 2010). "The ROS concentration of neutrophils in the induced sputum samples and the 8-iso-PGF2α concentration in the peripheral blood samples were higher in the severe asthma group (P = 0.012; P = 0.044), whereas there was reduced HDAC2 protein activity in PBMCs (P < 0.001)." (PMID 38131042, 2023). "This study suggested that regulation of HDAC2 expression level by BTK inhibition might be an alternative approach to obtaining sensitivity to corticosteroids in granulocytic asthma." (PMID 38178983, 2023). "Oxidative stress can affect the expression and activity of HDAC2 protein in a variety of ways, resulting in hormone resistance, which may adversely affect the treatment of asthma." (PMID 38131042, 2023).